CBX2 (chromobox 2)
Description:
Component of a Polycomb group (PcG) multiprotein PRC1-like complex, a complex class required to maintain the transcriptionally repressive state of many genes, including Hox genes, throughout development. PcG PRC1 complex acts via chromatin remodeling and modification of histones; it mediates monoubiquitination of histone H2A 'Lys-119', rendering chromatin heritably changed in its expressibility. Binds to histone H3 trimethylated at 'Lys-9' (H3K9me3) or at 'Lys-27' (H3K27me3) (By similarity). Plays a role in the lineage differentiation of the germ layers in embryonic development (By similarity). Involved in sexual development, acting as activator of NR5A1 expression.
Synonyms: MGC10561; M33; CDCA6; SRXY5
Tractability: PROTAC: UniProt records ubiquitination sites on it; ubiquitination databases record sites on it; a small molecule that binds it is known.
Target class: Epigenetic regulator; Reader; Methyl-lysine/arginine binding protein; Chromodomain
Gene: Protein-coding gene on chromosome 17 (79,778,148 to 79,787,983, forward strand). Ensembl gene ENSG00000173894.
Subcellular location: Nucleus; Chromosome
Subcellular location (Human Protein Atlas): Nucleoplasm
Pathways (Reactome):
Metabolism of proteins: SUMOylation of DNA damage response and repair proteins; SUMOylation of DNA methylation proteins; SUMOylation of RNA binding proteins; SUMOylation of chromatin organization proteins; SUMOylation of transcription cofactors
Cellular responses to stimuli: Oxidative Stress Induced Senescence
Developmental Biology: Differentiation of naive CD4+ T cells to T helper 2 cells (Th2 cells)
Gene expression (Transcription): RUNX1 interacts with co-factors whose precise effect on RUNX1 targets is not known
Signal Transduction: Regulation of PTEN gene transcription
Gene Ontology:
Molecular function: protein binding; histone H3K9me2/3 reader activity; chromatin binding
Biological process: development of primary sexual characteristics; negative regulation of transcription by RNA polymerase II; heterochromatin formation; negative regulation of DNA-templated transcription
Cellular component: chromosome; nucleoplasm; nucleus; PcG protein complex; PRC1 complex; chromatin; heterochromatin; euchromatin
Genetic constraint (gnomAD): Loss-of-function variants: 11 observed, 19.25 expected, observed/expected ratio (o/e) 0.57, 90% interval 0.36 to 0.95. The upper end of that interval is the gene's LOEUF score, 0.95, which puts it in group 4 of 6, group 1 being the genes least tolerant of losing a copy. Missense variants: 746 observed, 722.97 expected, observed/expected ratio (o/e) 1.03, 90% interval 0.97 to 1.1. Synonymous variants: 364 observed, 309.81 expected, observed/expected ratio (o/e) 1.17, 90% interval 1.08 to 1.28.
Homologues: Orthologues: chimpanzee CBX2 (99% identical), macaque CBX2 (97% identical), dog CBX2 (88% identical), pig CBX2 (87% identical), guinea pig CBX2 (83% identical), mouse Cbx2 (83% identical), rat Cbx2 (82% identical), tropical clawed frog syngr2 (45% identical), zebrafish cbx2 (42% identical), Caenorhabditis elegans set-31 (12% identical), Caenorhabditis elegans hpl-1 (6% identical). Paralogues in human: CBX4 (18% identical), CBX6 (18% identical), CBX8 (17% identical), CBX7 (15% identical), CBX3 (10% identical), CBX1 (10% identical), NPTXR (9% identical), CBX5 (9% identical).
Diseases named in the same sentence as CBX2 in open-access papers:
CBX2 is named in the same sentence as 62 diseases in open-access papers, as found by Europe PMC text mining. Sharing a sentence is not in itself a finding about the gene and the disease. The quoted sentences say what the papers report.
breast carcinoma (29 papers, 2014 to 2025). "The strong association of CBX2 and glycolysis deregulation with breast cancer aggressiveness suggests the therapeutic potential of targeting oncogenic CBX2 and/or glycolysis." (PMID 33400401, 2021). "CBX2 overexpression and amplification are closely associated with metastatic progression and shorter OS, especially in breast cancer." (PMID 34395271, 2021). "CBX2 promoted breast cancer cell proliferation; its overexpression caused upregulation of genes involved in cell cycle progression, and CBX2 overexpression was associated with poor 5-year survival." (PMID 33082469, 2020). "Furthermore, CBX2 overexpression was associated with poorer survival in the entire TCGA breast cancer cohort of 1084 patients with available survival data." (PMID 30820027, 2019). "CBX2 protein expression levels were inversely associated with prognosis in breast cancer patients." (PMID 29190923, 2017). "Recent studies have shown that the expression of CBX2 is closely related to the occurrence and development of osteosarcoma, ovarian cancer, breast cancer, liver cancer and prostate cancer." (PMID 39114365, 2024). "Clinically, the co-expression of high levels of USP27X and CBX2 in breast cancer tissues is indicative of a poor prognosis for patients with this disease." (PMID 38030604, 2023). "We observed similar effects in oestrogen receptor-positive breast cancer, and analysis of patient datasets suggested CBX2 inhibits RBL2 activity in other cancer types." (PMID 35884550, 2022). "Here, we investigate the role of the epigenetic regulatory protein CBX2 in aggressive forms of breast cancer, which have few therapeutic options." (PMID 35884550, 2022). "For CBX2, upregulation patterns were observed in bladder cancer, breast cancer (BC), colorectal cancer (CRC), GC, lung cancer and other cancer." (PMID 36140750, 2022). "The overexpression of CBX2 has been reported in breast cancer, where it promoted the progression of the disease by the PI3K/AKT signal pathway." (PMID 36292141, 2022). "CBX2 gene expression is highest in the basal-like breast cancer (BLBC) molecular subtype, of which 60–90% are TNBC." (PMID 35884550, 2022). "In this work, we delineate the conflicting roles of CBX2/7 in the regulation of glycolysis in breast cancer and establish their clinical relevance." (PMID 33400401, 2021). "Using transcriptomic and metabolomic data from breast cancer patients (N > 3000 combined), we performed pathway‐based analysis and identified outstanding roles of CBX2 and CBX7 in positive and negative regulation of glucose metabolism, respectively." (PMID 33400401, 2021). "This study provides a mechanistic basis for such roles, particularly from a metabolic perspective, thus imparting functional relevance to the biology of CBX2/7 in breast cancer." (PMID 33400401, 2021). "In conclusion, these data highlighted CBX2/7 as the important players, particularly in aggressive breast cancer, an observation concurring with their metabolic functions." (PMID 33400401, 2021). "Overall, these data demonstrate agreement between gene expression and metabolite data to indicate conflicting roles of CBX2/7 in breast cancer metabolism." (PMID 33400401, 2021). "Chromobox proteins‐CBX2/4/6/7/8, core components of canonical polycomb repressor complex 1, play essential roles in embryonic development and aberrantly expressed in breast cancer." (PMID 33400401, 2021). "Based on the multiomics data from breast tumors along with in vitro substantiation, we make a case for targeting of CBX2/7 and/or metabolic reprogramming in breast cancer for improved patient outcome." (PMID 33400401, 2021). "CBX2 is overexpressed in breast cancer and plays an essential role in tumor progression through the PI3K/AKT pathway." (PMID 33437202, 2021).
breast carcinoma (continued). "We found that CBX2 protein was highly expressed in the breast cancer tissues compared with normal tissues, and expression of CBX7 protein in breast cancer tissues was lower than tumor-adjacent normal tissues." (PMID 33082469, 2020). "From the development perspective, a CBX2 antagonist would be a promising therapeutic agent for breast cancer." (PMID 33082469, 2020). "The value of this tool is made clear by considering CBX2, the most promising OC identified, and its implications as a potential drug target for breast carcinoma." (PMID 30820027, 2019). "We observed that adherent MCF7 breast cancer cells grew, on average, 20% more slowly over the course of 7 days following CBX2 siRNA knockdown relative to a scrambled siRNA control (three-way ANOVA, P-value = 7.0 × 10−7)." (PMID 30820027, 2019). "Multiple lines of evidence lend support to CBX2 as a potential drug target against aggressive subtypes of breast carcinoma." (PMID 30820027, 2019). "To demonstrate the utility of oncomix, we applied this approach to RNA-seq data from the breast cancer cohort of The Cancer Genome Atlas (TCGA) and identified a set of five OCs (CBX2, NELL2, EPYC, SLC24A2, and LAG3)." (PMID 30820027, 2019). "The predicted function of CBX2 was confirmed in vitro, providing the first experimental evidence that CBX2 promotes breast cancer cell growth." (PMID 30820027, 2019). "CBX2 is an oncogene candidate that should be further explored as a potential drug target for aggressive types of breast cancer." (PMID 30820027, 2019). "To investigate the role of CBX2 in promoting breast cancer growth, we performed genetic knockdown of CBX2 in MCF7 breast cancer cells." (PMID 30820027, 2019). "Computational and experimental evidence point to the role of CBX2 as a regulator of breast cancer cell growth." (PMID 30820027, 2019). "CCLE analysis demonstrated that mRNA expression level of CBX2 in breast cancer listed the fifth highest among all cancer types." (PMID 29190923, 2017). "CBX2 transcripts were 9.378-fold elevated in breast cancer samples as compared with normal tissues in a dataset with 593 samples that derived from TCGA database." (PMID 29190923, 2017). "Previous studies have shown that CBX2 promotes breast cancer cell growth; CBX2 depletion inhibits the proliferation of gastric cancer and colorectal cancer cells; and CBX2 regulates proliferation and apoptosis via the phosphorylation of YAP in hepatocellular carcinoma." (PMID 39793896, 2025). "There are various studies about the function of CBX2 in breast cancer." (PMID 37489460, 2023). "We have therefore identified novel mechanisms by which CBX2 promotes breast cancer growth and provide evidence that inhibition of CBX2 may be a novel therapeutic strategy." (PMID 35884550, 2022). "Altogether, the results of this work postulate that CBX2‐driven metabolic reprogramming may be a target of interest for aggressive breast cancer therapy." (PMID 33400401, 2021). "In summary, this work identifies novel cross talk between CBX2/7 and breast tumor metabolism, and the results presented may have implications in strategies targeting breast cancer." (PMID 33400401, 2021). "CBX2 and CBX7 as the most differentially expressed isoforms in breast tumors compared to normal and the only two members whose expression is associated with breast cancer aggressiveness highlight the biological relevance of their determined metabolic roles." (PMID 33400401, 2021). "Regardless, CBX2/7 expression status informs about the metabolic phenotype of breast tumors, patient outcome, and sensitivity to anticancer drugs with potential implications in current or future strategies targeting clinical breast cancer." (PMID 33400401, 2021). "CBX2 may serve as a potential therapeutic strategy against aggressive breast cancers, due to its low expression in healthy female tissues, available pharmacologic inhibitors and association with poor survival." (PMID 30820027, 2019).
breast carcinoma (continued). "Our results indicate that CBX2 may serve as a driver of breast cancer and represent a novel therapeutic target in aggressive subtypes of breast cancer, such as HER2+ and basal-like." (PMID 30820027, 2019). "Although prior associative computational studies suggest that CBX2 is linked to breast cancer, no study has experimentally demonstrated a role for CBX2 in breast carcinogenesis." (PMID 30820027, 2019). "Third, CBX2 inhibition via genetic knockdown impedes the growth of breast cancer cells, which suggests that CBX2 may have an important role regulating breast cancer growth." (PMID 30820027, 2019). "Also, the data presented warrants a better understanding of CBX2/7 biology and invite further research into how these readers of same histone code (trimethylation of lysine residue of H3) differentially alter metabolic reprogramming in breast cancer." (PMID 33400401, 2021). "In addition, CBX2 was overexpressed in breast cancer with poor prognosis, and CBX2 downregulation could inhibit breast tumorigenesis in vivo and vitro." (PMID 33082469, 2020). "CBX2 may be an oncogene and a potential therapeutic target for breast cancer." (PMID 33082469, 2020). "It was reported that CBX2 overexpression occurs in a wide range of human tumors, including lung cancer, HCC, breast cancer, and so on." (PMID 36159831, 2022). "Together, these results hint at the role of CBX2 and CBX7 in modulating mTORC1 pathway to promote aerobic glycolysis in breast cancer." (PMID 33400401, 2021). "Using the integrative approach, we attempt here to delineate the role of aberrant CBX expression in metabolic reprogramming and identify CBX2 and CBX7 (referred as CBX2/7, hereafter) as antagonistic regulators of aerobic glycolysis in breast cancer." (PMID 33400401, 2021). "Overall, these in vitro results were found to be consistent with the findings of the transcripto‐metabolomic analysis and validated the roles of CBX2 and CBX7 in metabolic reprogramming of breast cancer." (PMID 33400401, 2021). "While a number of CBX proteins, such as CBX2, 4, 7, and 8, have been shown to play vital roles in breast cancer progression, the specific function of CBX6 in breast cancer progression remains to be elucidated." (PMID 30655550, 2019). "We also noticed that other amplified cPRC1 genes, including CBX2/4/8 and PCGF2, exhibited distinct expression patterns when categorized by breast cancer subtype." (PMID 30139998, 2018). "Our finding demonstrated that, through using Xena database analysis, the expression of CBX2 in Basal-like and HER-2 subtypes was significantly higher than Luminal subtypes breast cancer." (PMID 29190923, 2017). "Furthermore, we provide evidence for the role of mammalian target of rapamycin complex 1 signaling in mediating contrary effects of CBX2 and CBX7 on breast cancer metabolism." (PMID 33400401, 2021). "CBX2 and CBX7 play oncogenic and tumor‐suppressive roles, respectively, in breast cancer." (PMID 33400401, 2021). "CBX2, CBX4, CBX6, CBX7, and CBX8 are subunits of distinct polycomb repressive 1 complexes that have important functions in the development and progression of breast cancer." (PMID 33082469, 2020). "CBX2 plays a role in epigenetic regulation and hematopoietic stem cell differentiation, whereas the STK32B gene is one of several serine/threonine kinases (STK32B, STK36, and STK39) with similar gene expression patterns in basal-like breast cancers." (PMID 24885002, 2014). "Rather, overall functions of CBX2/7 (not necessarily antagonistic) may be defining sensitivities of breast cancer cell lines." (PMID 33400401, 2021). "Considering the complex and heterogeneous nature of glycolytic regulation concerning the players and mechanism involved, unraveling the mTORC1‐mediated metabolic roles CBX2 and CBX7 may improve our understanding about how glucose metabolism is regulated in breast cancer." (PMID 33400401, 2021).
breast carcinoma (continued). "Notably, only CBX2/7 correlated with subtype aggressiveness, and not others, a striking similarity to the correlation of glycolysis deregulation with breast cancer aggressiveness." (PMID 33400401, 2021). "However, RNF2, PCGF2, and CBX2/4/8 expression was higher in all four breast cancer stages compared to normal breast tissue, suggesting that their overexpression was not predictive of breast cancer aggressiveness." (PMID 30139998, 2018).
prostate carcinoma (16 papers, 2016 to 2025). A carcinoma that arises from epithelial cells of the prostate gland. "This was surprising given the fact that PI3K/AKT-signalling has also been associated with CBX2 in advanced prostate cancer and GBM." (PMID 35884550, 2022). "This inhibitor blocks CBX2-facilitated neuroendocrine differentiation in prostate cancer, mainly through de-repressing AR signaling in neuroendocrine differentiated prostate cancer cells." (PMID 34617019, 2021). "Elevated expression of CBX2 at both the transcriptional and translational levels was observed in aggressive prostate cancer." (PMID 32742466, 2020). "In breast and prostate cancers, they reported that CBX2 upregulation and amplification significantly correlated with metastatic progression and lower overall survival." (PMID 30478317, 2018). "CBX2 depletion reduced cell viability and promoted apoptosis in metastatic prostate cancer, suggesting that CBX2 drives key regulators of cell proliferation and metastasis." (PMID 30478317, 2018). "We identified the polycomb group (PcG) member and epigenetic reader CBX2 as the most highly expressed PcG gene in metastatic and castration-resistant prostate cancers." (PMID 26877821, 2016). "This inhibitor blocks CBX2, inducing neuroendocrine differentiation in prostate cancer cells." (PMID 40175347, 2025). "CBX2 depletion abolished cell viability and induced caspase-3-mediated apoptosis, suggesting that CBX2 may be a novel therapeutic target for advanced prostate cancer." (PMID 35892678, 2022). "Notably, a recent study in prostate cancer indicated that CBX2- and CBX8-containing PRC1 promotes the progression of prostate cancer to a highly aggressive neuroendocrine tumor subtype." (PMID 27449098, 2016). "Functional analysis revealed that CBX2 is critical for prostate cancer cell survival." (PMID 26877821, 2016). "Additionally, SW2_152F has been proven to inhibit the growth of triple-negative breast cancer cells and the neuroendocrine differentiation of prostate cancer cells, which indicated that CBX2 inhibitor could be a pan-cancer therapeutic agent." (PMID 36566204, 2022). "Then we further clarified the expression of CBX family members in prostate cancer, which result showed that CBX5, CBX6 and CBX7 were significantly down-regulated in prostate cancer tissues, while CBX3, CBX2, CBX4 and CBX8 was notably up-regulated." (PMID 40861818, 2025). "Taken together with observations in other types of cancer, it seems likely that the PRC1 and specifically, CBX2, are novel therapeutic targets not only for HGSOC, but potentially for breast and prostate cancers." (PMID 30478317, 2018).